ERCC5 (ERCC excision repair 5, endonuclease)
Diseases named in the same sentence as ERCC5 in open-access papers (continued):
Sharing a sentence is not in itself a finding about the gene and the disease.
lung carcinoma (10 papers, 2010 to 2024). "In conclusion, patients who carry the allele A of ERCC5 rs873601 are the protective allele in the prognosis of lung cancer treated with platinum-based chemotherapy." (PMID 38137354, 2023). "In conclusion, the variants of ERCC5 rs873601 were significantly associated with the prognosis in lung cancer patients treated with platinum-based chemotherapy." (PMID 38137354, 2023). "In the other investigation, ERCC5 rs4771436 and rs1047768 genotypes were reported to be associated with an increased risk of lung cancer patients." (PMID 38137354, 2023). "As we analyzed, the genomic polymorphisms ERCC5 rs873601 (G>A) were significantly associated with the overall survival (OS) of lung cancer patients in the recessive model (p = 0.031)." (PMID 38137354, 2023). "In other populations of the coal-mining region, the genomic variants of ERCC5 rs17655 were associated with lung cancer risk significantly." (PMID 38137354, 2023). "Multivariable logistic regression was used to investigate the association of ERCC1 and ERCC5 SNPs with lung cancer risk." (PMID 35069899, 2022). "We report for the first time a significant association between ERCC5 SNPs rs4771436 and rs1047768 with lung cancer risk progression in Liaoning Province." (PMID 35069899, 2022). "ERCC5 rs4771436 and rs1047768 were found to increase lung cancer risk, especially in men or those aged ≤60 years." (PMID 35069899, 2022). "Taken together, our results indicate that ERCC5 SNPs have a significant association with lung cancer risk progression." (PMID 35069899, 2022). "Specifically, we found that carriers of the ERCC5 rs4771436 GG genotype, the recessive model (GG vs. GT+TT) and the ERCC5 rs1047768 CC genotype, the recessive model (CC vs. CT+TT) showed a significantly increased risk of lung cancer (P<0.05)." (PMID 35069899, 2022). "Haplotype-base risk prediction of SNPs in ERCC1 and ERCC5 genes for lung cancer was performed using the HaploView." (PMID 35069899, 2022). "The ERCC5 rs17655GG was associated with an increased risk of lung cancer, and it may be associated with lung cancer susceptibility in the Chinese population." (PMID 38137354, 2023). "We found that the ERCC5 rs873601 plays a critical role in the resistance of platinum-based chemotherapy in lung cancer patients, which can perfect the investigation of ERCC5 gene mutations in lung cancer." (PMID 38137354, 2023). "The ERCC5 rs4771436 and rs1047768 genotypes are associated with the risk of lung cancer." (PMID 38137354, 2023). "Our findings suggest that ERCC5 might be a candidate gene for lung cancer susceptibility in the Han Chinese population." (PMID 35069899, 2022). "ERCC5 rs4771436 and rs1047768 had a significant association with lung cancer risk progression." (PMID 35069899, 2022). "ERCC5 as an important component in the repair pathway of platinum-induced damage, plays an important role in the prognosis of lung cancer patients." (PMID 38137354, 2023). "As a crucial member of the DNA damage and repair system, there are plenty of reports about ERCC5 and lung cancer." (PMID 38137354, 2023). "There were also investigations about ERCC5 and lung cancer prognosis, ERCC5 (rs2094258 and rs2296147) was reported to be related to progression-free survival (PFS) in NSCLC patients treated with platinum-based chemotherapy." (PMID 38137354, 2023). "In men, the ERCC5 rs1047768 the recessive model (CC vs. CT+TT) conferred a 3.00-fold increase in lung cancer progression." (PMID 35069899, 2022). "We found that the ERCC5 rs4771436 GG genotype, the recessive model (GG vs. GT+TT) and the ERCC5 rs1047768 CC genotype, the recessive model (CC vs. CT+TT) conferred increases in lung cancer progression in individuals aged ≤60 years." (PMID 35069899, 2022). "Here, we investigated the link between SNPs in DNA damage repair pathway genes and susceptibility to lung cancer by studying three ERCC1 and two ERCC5 SNPs in a Chinese Han population." (PMID 35069899, 2022).
lung carcinoma (continued). "Our findings provide experimental evidence to support the use of ERCC1 and ERCC5 SNPs as potential biomarkers of specific types of lung cancer." (PMID 35069899, 2022). "Thus, it is reasonable to speculate that inter-individual variation in CEBPG expression combined with variation in ERCC5 cis-regulatory SNPs contributes to lung cancer risk determination through effect on regulation of one or both of the alternative ERCC5 transcripts." (PMID 28464886, 2017). "The ERCC5 rs873601 was related to overall survival in additive and recessive model in age > 56 years lung cancer patients (Additive model: p = 0.032; Recessive model: p = 0.004) and smoker patients in additive and recessive model (Additive model: p = 0.048; Recessive model: p = 0.018)." (PMID 38137354, 2023). "ERCC5 rs873601 may be a potential therapeutic target in the treatment of lung cancer patients, which is valuable and will be further investigated." (PMID 38137354, 2023). "ERCC5 may become a potential therapeutic target for the treatment of lung cancer patients, as important as HER2 and EGFR." (PMID 38137354, 2023). "The genotypes of ERCC5 rs873601 may be an attractive biomarker used to predict the prognosis of lung cancer patients treated with platinum-based chemotherapy." (PMID 38137354, 2023). "Additionally, the ERCC5 rs1047768 the recessive model (CC vs. CT+TT) conferred an increase in lung cancer progression in men." (PMID 35069899, 2022). "We found that carriers of the ERCC5 rs4771436 GG genotype, the recessive model (GG vs. GT+TT) and the ERCC5 rs1047768 CC genotype, the recessive model (CC vs. CT+TT) had increased risks of lung cancer." (PMID 35069899, 2022). "Furthermore, decreased expression of XPG/ERCC5 and CSB/ERCC6 has been demonstrated to increase the risk of lung cancer." (PMID 32850380, 2020). "In addition to its association with CRC, the ERCC5 Asp1104His polymorphism was considered to be related to HIV 21 and various cancers, such as breast and lung cancer 22, and it was associated with tumor stage and grade 23." (PMID 30517302, 2018). "Radiotherapy-resistant lung cancer cells have also shown an up-regulation of ERCC5." (PMID 23626689, 2013).
non-small cell lung carcinoma (9 papers, 2012 to 2024). A group of at least three distinct histological types of lung cancer, including non-small cell squamous cell carcinoma, adenocarcinoma, and large cell carcinoma. "It has been also found that the ERCC5 rs751402 genotype was associated with the treatment response in patients with advanced non-small-cell lung cancer treated with platinum-based chemotherapy." (PMID 38137354, 2023). "Inactivation of ERCC5 has been shown to result in increased sensitivity to cisplatin in a variety of cancers, including non-small cell lung cancer, epithelial ovarian cancer, and uroepithelial cancer." (PMID 31321084, 2019). "Some SNPs in NER pathway genes correlated with toxicity in advanced non-small-cell lung cancer patients treated with chemotherapy, especially for SNPs of MMS19L, RRM1 and ERCC5, may have some effect to predict the adverse events of chemotherapy in NSCLC patients." (PMID 23118991, 2012).
bladder cancer (7 papers, 2008 to 2024). "In this work, we have conducted a case-control study in order to assess the effect of tobacco and three genetic polymorphisms in XPC, ERCC2 and ERCC5 genes (rs2228001, rs13181 and rs17655) in bladder cancer development in Tunisia." (PMID 21426550, 2011). "To test this hypothesis, we genotyped Lys939Gln genotype (A > C; rs2228001), ERCC2 Lys751Gln (rs13181) and ERCC5 Asp1104His (G > C; rs17655) polymorphisms in our ongoing hospital-based case-control study of Bladder cancer in a population from Tunisia." (PMID 21426550, 2011). "Another report on 98 patients with bladder cancer showed that mutations in DNA repair genes (CHEK2, ERCC5, GEN1, MLH1, PALB2, RAD50, RAD51B and RECQL4) are associated with an unfavorable cancer prognosis and 22% of patients had a mutation." (PMID 35395863, 2022). "Among variants which were studied in association with bladder cancer we note Lys939Gln genotype (A > C; rs2228001) in XPC gene, Lys751Gln (rs13181) in ERCC2 gene and Asp1104His (G > C; rs17655) in ERCC5 gene." (PMID 21426550, 2011). "The NER pathway has been reported to be the most significant modulator of bladder cancer risk and implicated many enzymes such as Xeroderma pigmentosum type C, D and G (XPC, ERCC2 and ERCC5)." (PMID 21426550, 2011). "Garcia-Closas evaluated the influence of common genetic variation in the NER pathway on bladder cancer risk by analyzing 22 single nucleotide polymorphisms (SNP) in seven NER genes (XPC, RAD23B, ERCC1, ERCC2, ERCC4, ERCC5, and ERCC6)." (PMID 19055767, 2008). "When we investigated the effect of genetic polymorphisms in bladder cancer development we have found that ERCC2 and ERCC5 variants were not implicated in the bladder cancer occurrence." (PMID 21426550, 2011).
progeria (7 papers, 2014 to 2026). "XPG, also called ERCC5, is a major DDR endonuclease, whose deficiency results in severe developmental defects, progeria and cancer." (PMID 35230528, 2022).
skin cancer (7 papers, 2016 to 2024). "Indeed, ERCC5 has been associated with an increased risk of developing skin tumors (basalomas, squamous cell carcinomas, melanomas)." (PMID 33821390, 2021). "Finally, a LoF variant was identified in the DNA repair gene ERCC5, in which homozygous mutations increase the skin cancer risk, and a damaging missense variant was mapped to FAH and causes an autosomal-recessive disorder characterized by progressive liver disease with increased liver cancer risk." (PMID 35495172, 2022). "Accordingly, all five specific skin cancer genes from the NER class - DDB2, ERCC3, ERCC5, XPA, and XPC - are associated with UV-sensitive skin." (PMID 26856619, 2016).
xeroderma pigmentosum group G (7 papers, 2012 to 2025). Any xeroderma pigmentosum in which the cause of the disease is a mutation in the ERCC5 gene. "ERCC5 is a vital constituent of the NER mechanism and is called xeroderma pigmentosum group G (XPG)." (PMID 36686735, 2022).
laryngeal carcinoma (5 papers, 2016 to 2022). Carcinoma that arises from the laryngeal epithelium. "Polymorphisms in other NER genes including ERCC1, ERCC2, ERCC3, ERCC4, ERCC5, and XPA have also been reported to pose as an increased risk in Laryngeal Cancer." (PMID 30410671, 2018).
COFS syndrome (4 papers, 2019 to 2024). Cerebrooculofacioskeletal (COFS) syndrome is a rare genetic disorder, belonging to a family of diseases of DNA repair, characterized by a severe sensorineural involvement. "According to a review of 59 cases of ERCC5 mutations, cerebrooculofacioskeletal syndrome (COFS) occurred in 16 cases, XP in 19 cases, and XP/CS in 24 cases." (PMID 40626125, 2024). "The fetus was found to be compound heterozygous for two different ERCC5 mutations, confirming the clinical suspect of COFS syndrome." (PMID 33766032, 2021). "Due to the prenatal findings, a COFS syndrome was suspected and further genetic investigation focusing on responsible genes were carried out: ERCC5, ERCC6 and FKTN genes (candidate genes included in the ILLUMINA Trusightone Clinical Exome Sequencing panel)." (PMID 33766032, 2021). "At the moment, four different genes are known to cause COFS syndrome: ERCC6 (COFS1, MIM #214150), ERCC2 (COFS2, MIM #610756), ERCC5 (COFS3, MIM #616570), and ERCC1 (COFS4, MIM #610758)." (PMID 33766032, 2021). "In the first case the COFS syndrome remained undiagnosed, while in the second case, due to prenatal findings of arthrogryposis and cataract, genetic investigation focusing on responsible genes of COFS (ERCC5, ERCC6 and FKTN genes) was carried out." (PMID 33766032, 2021).
liver cancer (4 papers, 2020 to 2024). An epithelial or non-epithelial malignant neoplasm that arises from the liver. "Significant differences in genotype distribiution between control, cirrhosis, and liver cancer groups were demonstrated for ERCC5 variants." (PMID 33171788, 2020). "In addition, ERCC5 gene polymorphisms (rs2016073, rs751402, rs2094258, rs2296147, and rs2296148) were found to be associated with cirrhosis and liver cancer." (PMID 40626125, 2024).
melanoma (4 papers, 2012 to 2021). A malignant, usually aggressive tumor composed of atypical, neoplastic melanocytes. "It has been observed that deficiency of ERCC5 may result in severe autosomal recessive diseases including XP, CS and TTD characterized by solar hypersensitivity of the skin, high predisposition for developing cancers (mainly epithelial and melanoma) on areas exposed to sunlight." (PMID 22815677, 2012).
sarcoma (4 papers, 2014 to 2022). A usually aggressive malignant neoplasm of the soft tissue or bone. "In addition, the genotyping of the SNPs rs17655 (Lys751Gln) in ERCC5 and rs13181 (Asp1104His) in ERCC2 revealed the potential implication of the Asp1104His polymorphism in the occurrence of chromosomal translocations associated with specific sarcoma subtypes." (PMID 35955506, 2022).
squamous cell carcinoma (4 papers, 2016 to 2021). A carcinoma arising from squamous epithelial cells. "In squamous cell carcinoma, rs4150558, rs2290280, rs8067195 were significantly associated with anemia, rs3786136 was significantly related to thrombocytopenia, ERCC5 presented consecutive significant signals in response rate." (PMID 28924235, 2017).
cervical cancer (3 papers, 2019 to 2022). A primary or metastatic malignant neoplasm involving the cervix. "In conclusion, these data demonstrate that exosomal miR-155-5p suppresses ARID2 expression via ERCC5-NF-κB signaling to promote invasion in cervical cancer." (PMID 31595161, 2019). "Most importantly, we determined that miR-155-5p was directly transferred from HIV-1-infected T cells to cervical cancer cells via exosomes and promoted invasion by decreasing the expression of its target gene ARID2 to activate the ERCC5-NF-κB signaling pathway." (PMID 31595161, 2019).
esophageal cancer (3 papers, 2012 to 2022). A primary or metastatic malignant neoplasm involving the esophagus. "Another strong evidence of association was that rs2296147 (T vs. C) mutant of ERCC5 could significantly downregulate the susceptibility of esophageal cancer in Asians under allelic and dominant genetic models." (PMID 36033436, 2022). "To date, some studies have reported that polymorphisms in ERCC5 are associated with risk of cancers of the breast, lung, skin and bladder, but there is only one published study of a nonsynonymous SNP (rs17655) and esophagus cancer in Caucasians with a small sample size." (PMID 22848513, 2012).
hepatocellular carcinoma (3 papers, 2017 to 2023). A malignant tumor that arises from hepatocytes. "Another study reported that the expression level of ERCC5 was significantly increased in hepatocellular carcinoma, and high ERCC5 expression conferred poor prognosis." (PMID 36803971, 2023).
thyroid cancer (3 papers, 2017 to 2022). "In TC, among those over-expressed in males, we found PPARG, previously reported in thyroid carcinomas, ERCC5, MYH11, LEMD2, ZNF133, and IDH1, the latter found to be mutated in thyroid carcinomas." (PMID 32849808, 2020). "Using this approach, two genes, namely ERCC5 and MGMT were significantly associated (PGene < 0.05) with PTC susceptibility, suggesting that DR, BER, and NER DNA repair mechanisms may all play a role in the development of thyroid cancer." (PMID 28499365, 2017).
Cirrhosis (2 papers, 2020 to 2024). A chronic disorder of the liver in which liver tissue becomes scarred and is partially replaced by regenerative nodules and fibrotic tissue resulting in loss of liver function. "Moreover, it was proposed that two ERCC5 gene polymorphisms (rs229614 and rs2296148) may be important targets for cirrhosis." (PMID 33171788, 2020).
osteosarcoma (2 papers, 2021 to 2023). A usually aggressive malignant bone-forming mesenchymal neoplasm, predominantly affecting adolescents and young adults. "The osteosarcoma sample presented mutations involving ATRX, ERCC5, and COL1A1, while the leiomyosarcoma case showed EXT2, DNM2, and PSIP1 alterations." (PMID 36673024, 2023). "However, the fact that the osteosarcoma greatly differs from the other histotypes, along with the presence of novel alterations in both cases (e.g., ERCC5 and PSIP1), highlights the need to further explore these rare entities." (PMID 36673024, 2023).
uterine cancer (2 papers, 2021 to 2022). Primary or metastatic malignant neoplasm involving the uterine corpus and/or the cervix. "Interestingly, a patient’s relative was affected by a uterine carcinoma, that is also reported to be also be associated to the ERCC5 p.Q1002X." (PMID 33821390, 2021).
Xeroderma pigmentosum complementation group G (2 papers, 2017 to 2021). Xeroderma pigmentosum complementation group G (XPG) is an extremely rare subtype of xeroderma pigmentosum (XP; see this term), a rare photodermatosis predisposing to skin cancers. "Homozygous or compound heterozygous mutation in ERCC5 are associated to the xeroderma pigmentosum complementation group G (XPG), a rare disease characterized by photosensitive erythema, keratoses and skin and eye disorders due to a high sensitivity to UV radiations." (PMID 33821390, 2021).
bladder tumors (1 paper, 2011). "Finally, we have reported that the SNP in the XPC, ERCC2 and ERCC5 genes don't affect the bladder tumors phenotype." (PMID 21426550, 2011).
Cachexia (1 paper, 2021). Severe weight loss, wasting of muscle, loss of appetite, and general debility related to a chronic disease. "An ERCC5 mutant mouse model presented premature aging features, including cachexia and osteoporosis, with pronounced degenerative phenotypes in both liver and brain." (PMID 34113558, 2021).
chronic bronchitis (1 paper, 2018). A type of chronic obstructive pulmonary disease characterized by chronic inflammation in the bronchial tree that results in edema, mucus production, obstruction, and reduced airflow to and from the lung alveoli. "ERCC5 SNP rs4150275 association with chronic bronchitis was identified in a set of Lung Health Study (LHS) COPD GWAS SNPs restricted to those in putative regulatory regions within the targeted genes, and this association was validated in the COPDgene non-hispanic white (NHW) GWAS." (PMID 29506519, 2018). "Moreover, by integrating the BEC RNAseq data with COPD GWAS, ENCODE, and GTEx databases, we identified ERCC5 SNP rs873601 as a plausible functional connection between ERCC5 DAE (measured at rs17655), and association of rs4150275 with chronic bronchitis in COPD GWAS." (PMID 29506519, 2018).
colon adenocarcinoma (1 paper, 2021). "In colon adenocarcinoma (COAD) and KIRC, ERCC5 expression was inversely correlated with the number of exome-wide mutations, whereas these two variables exhibited a positive and weak relationship in kidney renal papillary carcinoma (KIRP)." (PMID 34966786, 2021).
colon cancer (1 paper, 2018). "Increased ERCC5 expression demonstrated significant predominance in worse T stage and presence of distant metastasis in colon cancer." (PMID 29568775, 2018). "For colon cancer, high ERCC3 expression was related to better T stage; ERCC5 expression indicated deeper T stage and distant metastasis; DDB2 expression suggested earlier TNM stage." (PMID 29568775, 2018).
desmoid tumor (1 paper, 2024). A desmoid tumor (DT) is a benign, locally invasive soft tissue tumor associated with a high recurrence rate but with no metastatic potential. "In a small series of patients with desmoid tumors, disease-causing variants were identified in CHEK2, ERCC5, BLM, MSH6, and PALB2; however, none of these genes has been shown to be associated with increased risk of having desmoids." (PMID 38540414, 2024).